SIN3A (SIN3 transcription regulator family member A)
Diseases named in the same sentence as SIN3A in open-access papers (continued):
Sharing a sentence is not in itself a finding about the gene and the disease.
lymphoma (3 papers, 2010 to 2024). A malignant (clonal) proliferation of B- lymphocytes or T- lymphocytes which involves the lymph nodes, bone marrow and/or extranodal sites. "In that study, microarray data from Oncomine was analyzed and showed that SIN3A mRNA was significantly reduced in lung, renal, liver, and gastric tumors and lymphoma compared to normal tissue." (PMID 27780928, 2016). "GFI-1, Sin3A, PRMT5 and CCAR2 genes were uniformly expressed at high levels also in SUP-M2 cells, thus confirming their potential relevance in lymphoma." (PMID 39478125, 2024).
Stroke (3 papers, 2013 to 2019). Sudden impairment of blood flow to a part of the brain due to occlusion or rupture of an artery to the brain. "Our results show that the physical association of many lncRNAs with Sin3A and coREST increase significantly following stroke." (PMID 24063527, 2013). "We currently evaluated whether stroke-responsive lncRNAs interact with Sin3A and coREST, the CMPs associated with REST." (PMID 24063527, 2013). "Since Sin3A and coREST play important roles in post-stroke neuronal death, lncRNAs enriched with Sin3A and coREST show great potential regulatory values in ischemic stroke." (PMID 29651234, 2018). "Some Sin3A-enriched lncRNAs transcribed from intragenic loci that are particularly relevant to stroke, such as the transcription factor Fos, Dclk1 and the astrocytic activation marker GFAP." (PMID 24063527, 2013). "Our data support this by showing that a majority of the stroke-induced lncRNAs were bound to Sin3A or coREST with only three common lncRNAs that bound to both." (PMID 24063527, 2013). "Majority of the lncRNAs that showed significantly increased binding to Sin3A and coREST after stroke are intergenic (65%) or intragenic (sense exon or intron; 28%), while 7% are either bidirectional or antisense in origin." (PMID 24063527, 2013). "For the top 50 stroke-induced lncRNAs (up-regulated from 7- to 93-fold over sham), only seven showed increased enrichment with Sin3A and three showed increased enrichment with coREST." (PMID 24063527, 2013). "This suggests that the Sin3A- and coREST-enriched lncRNAs induced after stroke might play important roles in modifying the post-ischemic epigenetic landscape by modulating the REST-mediated gene silencing." (PMID 24063527, 2013). "Interestingly, the Dclk1 locus produced two lncRNAs, both of which were significantly induced after stroke and showed increased binding to Sin3A compared with sham." (PMID 24063527, 2013). "Together, this demonstrates that the enrichment of lncRNAs with Sin3A and coREST is not an artifact of an overall increase in lncRNA gene expression after stroke, but instead selective recruitment by these proteins." (PMID 24063527, 2013). "Twelve lncRNAs showed increased binding to both Sin3A and coREST after focal ischemia, but were not induced in their expression after stroke." (PMID 24063527, 2013). "Importantly, of 537 lncRNAs significantly induced (≥ 2-fold) at 6 h of reperfusion after transient MCAO, the top 17 stroke-induced lncRNAs (up-regulated from 22- to 93-fold over sham) were not enriched with either protein (Sin3A or coREST) evaluated by RIP." (PMID 24063527, 2013).
triple-negative breast carcinoma (3 papers, 2016 to 2022). An invasive breast carcinoma which is negative for expression of estrogen receptor (ER), progesterone receptor (PR), and human epidermal growth factor receptor 2 (HER2). "Overall, this data supports that SIN3A and SIN3B expression levels in cancer patients will depend on molecular subtype; and in triple negative breast cancer, lowered expression of SIN3A and higher expression of SIN3B may be associated with more aggressive disease progression." (PMID 27780928, 2016). "Interestingly, when analyzing triple negative breast cancers specifically, we noted that high SIN3A or low SIN3B mRNA expression correlated with longer relapse-free survival." (PMID 27780928, 2016). "However, high expression of SIN3A and low expression of SIN3B correlated with a longer relapse-free survival specifically in triple negative breast cancers (hazard ratios = 0.56 and 1.51; logrank P = 0.055 and 0.076 respectively for SIN3A and SIN3B)." (PMID 27780928, 2016). "It is also interesting to note that expression of several SIN3A and SIN3B target genes in our data sets are consistent with the relapse-free survival identified for SIN3A and SIN3B for patients with triple negative breast cancer." (PMID 27780928, 2016). "In our published work, we have established that the treatment of triple-negative breast cancer (TNBC) cell lines with SMI MS-905, which targets the interaction between the MAD1 (MXD1) and PAH2 domain of Sin3A, exhibits remarkable phenotypes both in vitro and in vivo." (PMID 35406744, 2022). "Moreover, we identified correlations of high SIN3A and low SIN3B mRNA expression with relapse-free survival specifically in triple negative breast cancers." (PMID 27780928, 2016).
breast tumor (2 papers, 2021 to 2023). "The SIN3A gene was associated with rs60381548 in the eQTL analysis of breast tumor in the present study." (PMID 34234117, 2021). "Collectively, these findings indicate that SAP30 promotes breast tumor growth, tumor angiogenesis, lymphangiogenesis, and distant metastasis in a SIN3A/3B-dependent manner." (PMID 37655663, 2023). "Collectively, these findings indicate that SIN3A and SIN3B phenocopy SAP30 to promote breast tumor angiogenesis, growth, and metastasis in vitro and in vivo." (PMID 37655663, 2023). "SIN3B, HDAC1, HDAC2, SUDS3, and RBBP4, but not SIN3A and SAP18, were also upregulated to a lesser degree in human breast tumors." (PMID 37655663, 2023). "Rather than being a corepressor, SAP30 coordinates with SIN3A/3B and MLL1 to increase chromatin accessibility and coactivate the transcription of genes involved in cell motility, angiogenesis, and lymphangiogenesis, leading to breast tumor growth and metastasis to distant organs." (PMID 37655663, 2023).
pancreatic cancer (2 papers, 2021 to 2024). "A main mechanism is that Snail can recruit HDAC1/2 and Sin3A complexes into the E‐cadherin promoter, then down‐regulate the expression of E‐cadherin, and promote the metastasis of pancreatic cancer." (PMID 33325150, 2021). "Moreover, Sin3A loss leads to decreased expression of Cxcl9, Ifng, and Tnfa in pancreatic tumor tissues, suggesting that SIN3A plays a distinct role in the regulation of the TIME, differing from that of SIN3B." (PMID 39316363, 2024).
prostate carcinoma (2 papers, 2023). A carcinoma that arises from epithelial cells of the prostate gland. "Both CTCF and SIN3A were found to have low depmap dependency scores for multiple prostate cancer cell lines." (PMID 37627195, 2023). "Both CTCF and SIN3A were observed to have overexpression in prostate cancer compared to normal tissue." (PMID 37627195, 2023). "An exploration of the prostate cancer GRN revealed a subnetwork comprised of two chromatin constituents, CTCF and SIN3A." (PMID 37627195, 2023). "In this study, further exploration of the GRNs of prostate cancer identified key transcriptional regulatory factors, CTCF and SIN3A." (PMID 37627195, 2023).
Rett syndrome (2 papers, 2014 to 2020). A severe neurodevelopmental disorder affecting the central nervous system.
sarcoma (2 papers, 2010 to 2022). A usually aggressive malignant neoplasm of the soft tissue or bone. "SIN3 transcription regulator family member A (SIN3A) and SP1 were suggested to be highly expressed in sarcoma." (PMID 35590288, 2022).
amnesia (1 paper, 2020). Pathologic partial or complete loss of the ability to recall past experiences ( AMNESIA, RETROGRADE) or to form new memories ( AMNESIA, ANTEROGRADE). "In summary, the findings of this study demonstrated that scopolamine-induced amnesia was associated with downregulated expression of miR-210/miR-183 and upregulated expression of SIN3A." (PMID 33183243, 2020). "The expression of SIN3A is closely correlated with electroacupuncture (EA) treatment efficacy of scopolamine-induced amnesia (SIA), but its underlying mechanisms remain to be further explored." (PMID 33183243, 2020). "Furthermore, treatment with EA alleviated scopolamine-induced amnesia in rats and was associated with upregulated expression of miR-210/miR-183 and downregulated expression of SIN3A." (PMID 33183243, 2020). "Also, since amnesia is closely related to the hippocampus of the brain, we further performed IHC on the hippocampus tissues of rats to analyze their expression of SIN3A." (PMID 33183243, 2020).
Autoimmunity (1 paper, 2024). The occurrence of an immune reaction against the organism's own cells or tissues. "Together, these data showing extensive tissue injury and rapid death indicate that Sin3a perform a vital role in Treg cells, with consequences for prevention of autoimmunity." (PMID 39156895, 2024). "Developmental deletion of Sin3a from Foxp3+ Tregs resulted in the rapid onset of fatal autoimmunity." (PMID 39156895, 2024). "When Sin3a deletion in Foxp3+ Tregs was induced following normal pre- and postnatal development, evidence of autoimmunity developed in sLNs and lungs." (PMID 39156895, 2024). "Mice with homozygous deletion of Sin3a in Foxp3+ Tregs developed severe autoimmunity and died within 15–22 days of birth." (PMID 39156895, 2024). "Sin3a deletion in Tregs resulted in the development of autoimmunity." (PMID 39156895, 2024). "The reasoning behind this was that Sin3a deletion from both suppressive and effector CD4+ T lineages would rescue the severe early-onset autoimmunity and fatality of Sin3a−/−FoxP3cre deletion." (PMID 39156895, 2024). "Following tamoxifen treatment, mice did not succumb to fatal autoimmunity, but like Sin3a−/−Foxp3cre mice, they had massive sLNs with pronounced follicles and germinal centers and developed PMN infiltrates and airway cuffing in the lungs." (PMID 39156895, 2024). "One explanation for why the induction of Sin3a deletion did not provoke the severity of autoimmunity present in Sin3a−/−Foxp3cre is that the role of Sin3a within Foxp3+ Tregs is of vital importance during fetal and postnatal development." (PMID 39156895, 2024). "Consistent with this, female heterozygous Sin3a−/+Foxp3cre mice did not develop fatal autoimmunity." (PMID 39156895, 2024). "Indeed, Sin3a−/−CD4cre mice did not develop fatal autoimmunity." (PMID 39156895, 2024). "However, unlike in Sin3a−/−FoxP3cre, the percentages and numbers of CD4+ and CD8+ T cells in the SLOs of Sin3a−/−CD4cre mice were greatly reduced, providing an explanation as to why these mice do not develop fatal autoimmunity." (PMID 39156895, 2024).
Beta-thalassaemia (1 paper, 2024). "Indeed, Sin3A is known to worsen Beta-thalassaemia severity, possibly inhibiting the action of KLF10 which is known to ameliorate symptoms in a range of Beta-Haemoglobinopathies32." (PMID 38862545, 2024).
brain tumors (1 paper, 2024). "These included REST and SIN3A, which inhibit neural differentiation and whose binding sites in PSCs, but not those in “other brain and neural samples” or “other brain tumors,” were enriched in MB-hyper regions." (PMID 38499326, 2024).
cerebellar disorder (1 paper, 2025). Diseases that affect the structure or function of the cerebellum. "Our findings highlight the central role of the Sin3A complex in orchestrating distinct stages of cerebellar GC lineage development and may provide insights into Sin3A-related cerebellar disorders and medulloblastoma in human." (PMID 41278648, 2025).
Cerebral ischemia (1 paper, 2018). Restriction of arterial blood supply to the brain associated with insufficient oxygenation to support the metabolic requirements of the tissue. "Studies have found that neuronal transcriptional repressor element-1 silencing transcription factor (REST) and its corepressors Sin3A and coREST were critical to neuronal death after cerebral ischemia." (PMID 29651234, 2018). "For example, lncRNA MRAK159688 enriched with both Sin3A and coREST expressed nearly three times compared to control whereas lncRNA EF094477 enriched with Sin3A increased more than six times after cerebral ischemia." (PMID 29651234, 2018).
COVID-19 (1 paper, 2022). A disease caused by infection with severe acute respiratory syndrome coronavirus 2. "Prominent expression of the transcription factor SIN3A has been demonstrated in premortem skin biopsies of severe COVID-19 patients, where it also correlates with disease severity." (PMID 36684608, 2022).
cystic fibrosis (1 paper, 2021). Autosomal recessive disorder caused by pathogenic variants in the CFTR gene (cystic fibrosis transmembrane conductance regulator), which encodes a chloride and bicarbonate channel expressed in epithelial cells, and follow the diagnosis criteria. "We previously reported that expression of a miR-138 mimic or knockdown of SIN3A in primary cultures of cystic fibrosis airway epithelia increased ΔF508-CFTR mRNA and protein levels, and partially restored CFTR-dependent chloride transport." (PMID 34717611, 2021).
ductal carcinoma in situ (1 paper, 2016). "In support of this, data analyzed from Oncomine revealed a trend towards decreased expression of SIN3A and increased expression of SIN3B in patients with triple negative invasive ductal carcinoma compared to ductal carcinoma in situ." (PMID 27780928, 2016).
Epstein-Barr virus infection (1 paper, 2022). An infection that is caused by Epstein-Barr virus. "Finally, four significant KEGG enrichment pathways were identified (P < 0.05): beta-Alanine metabolism (SMOX, HIBCH), Pathways in cancer (GLI2, AR, TXNRD3, TRAF3, FGF16), Non-homologous end-joining (MRE11), Epstein-Barr virus infection (TRAF3, PSMD13, SIN3A)." (PMID 36330154, 2022). "Finally, the results of KEGG enrichment analysis showed four significantly enriched pathways (P < 0.05): beta-Alanine metabolism (SMOX, HIBCH), Pathways in cancer (GLI2, AR, TXNRD3, TRAF3, FGF16), Non-homologous end-joining (MRE11), Epstein-Barr virus infection (TRAF3, PSMD13, SIN3A)." (PMID 36330154, 2022).
Hyperinsulinemia (1 paper, 2022). An increased concentration of insulin in the blood. "We identified at least one novel transcriptional repressor of the Insr gene, SIN3A, which was upregulated by hyperinsulinemia." (PMID 34921686, 2022). "Among them, Sin3a, Myc and Ets1 were upregulated by in vitro hyperinsulinemia." (PMID 34921686, 2022).
Hyperkeratosis (1 paper, 2013). Hyperkeratosis is a histopathological term defining a thickened stratum corneum and may be present in many different skin conditions, with many possible overlaps. "Second, the reduced amount of Sin3A and the impaired Sin3A co-repressor function led to derepression of differentiation specific genes, thereby contributing to the hyperkeratosis of the mutant epidermis." (PMID 24240174, 2013).
hypogonadotropic hypogonadism (1 paper, 2024). Abnormal ovarian or testicular function due to insufficient hormonal stimulation from the hypothalamic-pituitary axis. "Whether hypogonadotropic hypogonadism is due to haploinsufficiency of SIN3A or any of the other eight genes present in 15q24 is not known." (PMID 38528912, 2024).
Kallmann syndrome (1 paper, 2024). Kallmann syndrome (KS) is a developmental genetic disorder characterized by the association of congenital hypogonadotropic hypogonadism (CHH) due to gonadotropin-releasing hormone (GnRH) deficiency, and anosmia or hyposmia (with hypoplasia or aplasia of the olfactory bulbs). "In conclusion, these findings point to SIN3A as the gene in 15q24 related to the reproductive phenotype in patients with overlapping WITKOS and Kallmann syndrome." (PMID 38528912, 2024).
latent infection (1 paper, 2013). "Taken together, this data above strongly support our hypothesis that KAP1 and Sin3A particularly SUMO-2 modified forms are indeed sensitive to hypoxic stress and are recruited by the LANASIM motif during KSHV latent infection to silence the RTA promoter under normoxic conditions." (PMID 24278015, 2013).
leukemia (1 paper, 2016). A malignant (clonal) hematologic disorder, involving hematopoietic stem cells and characterized by the presence of primitive or atypical myeloid or lymphoid cells in the bone marrow and the blood. "It is reported that TNF-alpha, SIN3A and SIN3-HDAC complex have close relationship with leukemia." (PMID 26822725, 2016).
liver fibrosis (1 paper, 2024). "Overexpression of miR-144 in HSCs decreased SIN3A expression, whereas inhibition of miR-144 obviously elevated its expression in CCl4-induced liver fibrosis." (PMID 38725842, 2024). "Our data demonstrated that suppression of Sin3a expression in HSCs significantly accelerated the activation of HSCs in vitro and immensely exacerbated the degree of liver fibrosis in vivo." (PMID 38725842, 2024). "In conclusion, under the strike of CCl4 or BDL, oxidative stress drives miR-144 to aggravate liver fibrosis by inhibiting the SIN3A-p38 axis." (PMID 38725842, 2024). "Gain or loss-of-function data in vivo suggest that specific blockade of miR-144 in HSCs mitigated, overexpression of miR-144 in HSCs accelerated the development of experimental liver fibrosis by limiting the SIN3A-p38 axis." (PMID 38725842, 2024). "Additionally, immunohistochemistry staining from serial sections demonstrated that SIN3A protein levels were also increased in patients with liver fibrosis." (PMID 38725842, 2024). "To elucidate whether SINA3A was involved in the progression of liver fibrosis, we firstly transfected Sin3a siRNA in JS-1 cell lines." (PMID 38725842, 2024). "Moreover, miR-144 targeting SIN3A was also corroborated in mice with CCl4-induced liver fibrosis, which were administrated with AAV6-miR-144 agomir/antagomir." (PMID 38725842, 2024). "Nevertheless, the involvement of SIN3A in liver fibrosis is debated and controversial at present." (PMID 38725842, 2024). "MiR-144 downregulated Sin3A, and in line with this result, specific knockdown of Sin3a in HSCs remarkedly activated p38 MAPK signaling pathway to promote HSC activation, eventually exacerbating liver fibrosis." (PMID 38725842, 2024). "In the current study, we demonstrated for the first time that oxidative stress-related miR-144 was preferentially expressed in HSCs during liver fibrosis development, eventually fueling HSC activation and liver fibrogenesis by limiting the SIN3A-p38 axis." (PMID 38725842, 2024).
lupus (1 paper, 2024). "Moreover, crucial transcriptional regulators related to lupus such as HDACs/Sin3A, cAMP-responsive element-binding protein (CREB), and nuclear receptor corepressor 1 (NCoR1) were upregulated in both B6.Mecp2Tg1 and MRL/lpr when compared to B6 controls." (PMID 38524134, 2024).
mammary adenocarcinoma (1 paper, 2021). "In mammary adenocarcinoma cells, SIN3A interacts with STAT3 to silence tumor suppressor gene and inhibit cell survival." (PMID 35127514, 2021).
mental disorder (1 paper, 2025). A disease that has its basis in the disruption of mental process. "Apart from increased SIN3A protein levels in the hippocampus of suicide victims, no other association of this gene with mental disorders has been reported, particularly in blood." (PMID 40018685, 2025).